CKS1BP7 (CDC28 protein kinase regulatory subunit 1B pseudogene 7)
Synonyms: formerly CKS1; CKS1A
Gene: Processed pseudogene on chromosome 8 (80,644,939 to 80,645,173, reverse strand). Ensembl gene ENSG00000254331.
Diseases named in the same sentence as CKS1BP7 in open-access papers:
CKS1BP7 is named in the same sentence as 2 diseases in open-access papers, as found by Europe PMC text mining. Sharing a sentence is not in itself a finding about the gene and the disease. The quoted sentences say what the papers report.
cancer (1 paper, 2025). A tumor composed of atypical neoplastic, often pleomorphic cells that invade other tissues. "Interestingly, CKS1BP7, a non-SVA-associated copy, is expressed in about a third of breast cancer tumors, and overexpression of the CKS1B parent gene is associated with aggressive progression and poor prognosis in a number of cancers." (PMID 41199327, 2025).
CKS1BP7 also shares sentences with these, for which no sentence is quoted: invasive carcinoma (1 paper).